LINC01091 (long independently transcribed non-coding RNA 1091)
Gene: Long non-coding RNA gene on chromosome 4 (123,539,026 to 123,962,704, forward strand). Ensembl gene ENSG00000249464.
Diseases named in the same sentence as LINC01091 in open-access papers:
LINC01091 is named in the same sentence as 9 diseases in open-access papers, as found by Europe PMC text mining. Sharing a sentence is not in itself a finding about the gene and the disease. The quoted sentences say what the papers report.
gastric cancer (2 papers, 2022 to 2023). A primary or metastatic malignant neoplasm involving the stomach. "LINC01091 also seems to have a role in cancer, as it regulates tumorigenesis and metastasis in gastric cancer, and is also implicated to have a role in prostate cancer." (PMID 36290414, 2022). "LINC01091 can coordinate the microRNA-128-3p/ELF4/CDX2 axis and thus promote gastric cancer growth and metastasis by way of exosomes on one hand and can act as hub lncRNA in DNA methylation-related prognostic signatures of prostate cancer." (PMID 37822927, 2023).
asthenozoospermia (1 paper, 2022). "LINC01091 and LINC01359 were also found to be deregulated in the three main subtypes of male infertility, namely asthenozoospermia, teratozoospermia, and oligozoospermia." (PMID 36290414, 2022).
pancreatic cancer (1 paper, 2022). "In pancreatic cancer cells and tissues, qRT-PCR indicated the relative expression of LINC01091, LINC01133, TRPC7-AS1, and LINC00973." (PMID 36371178, 2022).
cardiovascular disease (1 paper, 2022). "In summary, the relationship betweenGAS5 and H19 and cardiovascular disease is relatively clear,but the relationship among MIR22HG, LINC01091, andcardiovascular disease requires further study." (PMID 39077137, 2022).
LINC01091 also shares sentences with these, for which no sentence is quoted: prostate carcinoma (2 papers); asthma (1); cancer (1); male infertility (1); teratozoospermia (1).